FEN1 (flap structure-specific endonuclease 1)
Diseases named in the same sentence as FEN1 in open-access papers (continued):
Sharing a sentence is not in itself a finding about the gene and the disease.
ovarian carcinoma (17 papers, 2020 to 2026). A malignant neoplasm originating from the surface ovarian epithelium. "With respect to ovarian cancer, the effects were partially caused by down-regulated expression of FEN1 mediated by miR-134-3p." (PMID 35779228, 2023). "In a clinical cohort, flap structure-specific endonuclease 1 (FEN1) is identified as a key molecule in DNA repair, and FEN1 overexpression is associated with poor survival after platinum chemotherapy of ovarian cancer patients." (PMID 35754835, 2022). "In clinical cohorts of ovarian cancers, we observed that tumors with low FEN1/low BRCA2 co-expression were associated with good PFS (p = 0.038) compared to tumors with high FEN1/high BRCA2 co-expression." (PMID 33919707, 2021). "In the current study, we show that FEN1, a key player in DNA repair, is overexpressed in ovarian cancer and associated with poor survival." (PMID 33919707, 2021). "In the current study, we validated in a larger cohort of ovarian tumors AND provide evidence that FEN1 overexpression is associated with an aggressive phenotype and predicts platinum resistance in ovarian cancer." (PMID 33919707, 2021). "Taken together, the data provide preclinical evidence that FEN1 is a promising synthetic lethality target for BRCA2 deficient ovarian cancers." (PMID 33919707, 2021). "Loss; gene inactivation or inhibition of FEN1 could re-sensitize platinum-resistant ovarian cancer cells to cisplatin." (PMID 35883563, 2022). "Since we had previously shown that POLβ or XRCC1 deficiency is a predictor of platinum sensitivity in ovarian cancers, we investigated whether a synthetic lethality relationship exists between FEN1 and either POLβ or XRCC1." (PMID 33919707, 2021). "Importantly, FEN1 inhibition was synthetically lethal in BRCA2 deficient or POLβ deficient ovarian cancer cells." (PMID 33919707, 2021). "In a small cohort of ovarian cancer, we provided preliminary evidence that FEN1 overexpression may also be associated with poor outcomes in ovarian cancers." (PMID 33919707, 2021). "We hypothesized that FEN1 could be a promising alternative synthetic lethality target in BRCA2 deficient ovarian cancers." (PMID 33919707, 2021). "Taken together, the data suggest that FEN1 nuclear expression may predict response to platinum chemotherapy in ovarian cancers, with higher expression associating with reduced treatment effectiveness." (PMID 33919707, 2021). "RESULTS: Our findings reveal that PGC-1β silencing sensitizes ovarian cancer cells to PARPi by impairing oxidative metabolism, reducing succinate levels and decreasing Fen1 succinylation and SUMOylation." (PMID 41530766, 2026). "In summary, this study revealed that miR-4324 suppressed ovarian cancer cell proliferation and adhesion by inhibiting FEN1 expression." (PMID 35246224, 2022). "Our study found that miR-4324 inhibited FEN1 expression, suppressed cell growth, and increased apoptosis in ovarian cancer cells." (PMID 35246224, 2022). "Overall, these results indicated that miR-4324 targets FEN1, thereby impairing the development of ovarian cancer." (PMID 35246224, 2022). "The results showed that miR-4324 expression was significantly decreased and FEN1 expression was enhanced in ovarian cancer tissues and cell lines." (PMID 35246224, 2022). "This study revealed that miR-4324 expression was significantly downregulated and FEN1 expression upregulated in ovarian cancer tissues and cell lines." (PMID 35246224, 2022). "When cisplatin was used to treat ovarian cancer, it was found that FEN1 expression was strongly induced and that the nuclear translocation of FEN1 depended on the physical interaction with Importin β." (PMID 35883563, 2022). "A study revealed that miR-134-3p, a FEN1 inhibitor, considerably decreased cell proliferation, migration, and invasion and increased apoptosis in human ovarian cancer." (PMID 35246224, 2022).
ovarian carcinoma (continued). "Whilst BRCA2 deficiency as a marker of platinum sensitivity has been well described in ovarian cancer cells, the data presented here provides evidence that FEN1 also has important roles in the repair of DNA damage induced by platinum agents." (PMID 33919707, 2021). "FEN1 depletion, gene inactivation, or inhibition re-sensitizes platinum-resistant ovarian cancer cells to cisplatin." (PMID 33919707, 2021). "Together, our data not only provide novel insights into the mechanism of resistance to FEN1 inhibitors but also reveal additional synthetic lethality opportunities in epithelial ovarian cancers." (PMID 33919707, 2021). "We conclude that FEN1 is a promising target for platinum chemo-sensitization and synthetic lethality application in ovarian cancers." (PMID 33919707, 2021). "Pre-clinically FEN1 blockade not only increased platinum sensitivity but was also synthetically lethal in BRCA2 and POLβ deficient ovarian cancer cells." (PMID 33919707, 2021). "MiR-134-3p inhibited the progression of ovarian cancer via targeting flap structure-specific endonuclease 1 in vitro." (PMID 34302635, 2021). "We conclude that FEN1 is an attractive anti-cancer target in epithelial ovarian cancers, and pharmacological targeting of the nuclease with more advanced small molecule inhibitors is a promising avenue for cancer therapy." (PMID 33919707, 2021). "Pre-clinically, FEN1 depletion or genetic inactivation reversed platinum resistance in ovarian cancer cells." (PMID 33919707, 2021). "Nevertheless, taken together, our data suggest that FEN1 is a valid target in the treatment of ovarian cancer and that further pharmaceutical development of FEN1 inhibitors is warranted." (PMID 33919707, 2021). "In the current study, we analyze the associations between 19 SNPs of six BER-related genes (hOGG1, APE1, PARP1, FEN1, LIG3 and XRCC1) and ovarian cancer risk by genotyping method in 196 patients and 272 controls." (PMID 33391423, 2021). "For example, FEN1 blockade re‐sensitises platinum‐resistant ovarian cancer cells to cisplatin." (PMID 37326412, 2023). "We identified miR-4324 and FEN1 as potential therapeutic targets for ovarian cancer treatment." (PMID 35246224, 2022). "FEN1 expression levels in ovarian cancer tissues were approximately double those of normal tissues." (PMID 35246224, 2022). "In the context of ovarian cancer, a previous study revealed that FEN1 could be a key biomarker of ovarian cancer owing to the increased expression of FEN1 mRNA and protein." (PMID 35246224, 2022). "Therefore, we identified miR-4324 and FEN1 as potential therapeutic targets for ovarian cancer treatment." (PMID 35246224, 2022). "Moreover, this study further demonstrated that miR-4324 targeted FEN1 and repressed cell growth and adhesion in ovarian cancer." (PMID 35246224, 2022). "FEN1 overexpression is associated with an increased aggressive phenotype and poor prognosis of cancer after cisplatin chemotherapy, while inhibition of Pol β or XRCC1 can enhance the sensitivity of ovarian cancer to cisplatin treatment." (PMID 35883563, 2022). "miR-4324 expression was negatively correlated with FEN1 expression in ovarian cancer tissues." (PMID 35246224, 2022). "Furthermore, the downregulation of FEN1 inhibited ovarian cancer cell growth and increased apoptosis." (PMID 35246224, 2022). "We hypothesized that miR-4324 could attenuate ovarian cancer progression by suppressing FEN1 expression." (PMID 35246224, 2022). "In this study, we sought to determine the functions of miR-4324 and FEN1 in ovarian cancer." (PMID 35246224, 2022). "miR-4324 inhibited FEN1 expression and repressed ovarian cancer progression." (PMID 35246224, 2022). "It is likely that miR-4324/FEN1 interaction could be a novel molecular target for ovarian cancer treatment in the future." (PMID 35246224, 2022). "Furthermore, we found, for the first time, that the effect of FEN1 on ovarian cancer cells was inhibited by miR-4324." (PMID 35246224, 2022).
ovarian carcinoma (continued). "miR-4324 and FEN1 expressions in ovarian cancer tissues and cell lines were measured via RT-qPCR." (PMID 35246224, 2022). "In vitro tests have found that FEN1 deletion or gene inactivation could reverse cisplatin tolerance in ovarian cancer cells, while FEN1 small-molecule inhibition increased platinum sensitivity." (PMID 35883563, 2022). "The data provides evidence that FEN1 is a promising predictive biomarker in ovarian cancer." (PMID 33919707, 2021). "Moreover, FEN1 overexpression in ovarian epithelial cancer was correlated with a high cancer grade and stage, and poorer survival." (PMID 34277392, 2021). "Moreover, FEN1 depletion or genetic inactivation re-sensitizes platinum resistant ovarian cancer cell lines to cisplatin." (PMID 33919707, 2021). "We conclude that FEN1 is a valid target for ovarian cancer therapy." (PMID 33919707, 2021). "Given its various roles in DNA metabolism and the emerging evidence of roles in cancer etiology, we hypothesized a key role for FEN1 in ovarian cancer pathogenesis." (PMID 33919707, 2021). "Moreover, FEN1 overexpression was correlated with a high grade and stage of ovarian epithelial cancer." (PMID 34277392, 2021). "Together the data provides evidence that FEN1 is a promising anti-cancer target in ovarian cancer." (PMID 33919707, 2021). "And using FEN1 inhibitors in lung and ovarian cancer could increase the antineoplastic effect of cisplatin and paclitaxel, by further enhancing the DNA damage." (PMID 32318339, 2020). "In addition, the data suggest that a small molecule blockade of FEN1 could be a promising anti-cancer approach in ovarian cancers." (PMID 33919707, 2021). "The effects of miR-4324 and FEN1 on cell proliferation, adhesion and apoptosis were determined by CCK-8, BrdU, colony formation, cell adhesion, Caspase-3 and western blot assays in ovarian cancer cell lines CaOV3 and OVCAR3, respectively." (PMID 35246224, 2022). "miR-4324 inhibited FEN1 expression and suppressed cell growth, while increasing apoptosis in CaOV3 and OVCAR3 ovarian cancer cells." (PMID 35246224, 2022). "However, the function of miR-4324 and FEN1 in ovarian cancer remains unclear." (PMID 35246224, 2022). "Thus, we speculated that FEN1 might be a tumor promoter in ovarian cancer." (PMID 35246224, 2022). "In this two-center case-control study, 19 potentially functional SNPs in six BER-related genes (hOGG1, APE1, PARP1, FEN1, LIG3 and XRCC1) was genotyped in 196 ovarian cancer cases and 272 cancer-free controls." (PMID 33391423, 2021). "However, in the current study, we did not observe selective toxicity for FEN1 inhibitor in ATM-deficient HeLa cells or MRE11 deficient ovarian cancer cells implying that this phenomenon could be cell line dependent." (PMID 33919707, 2021). "We have previously shown that FEN1 17, RPA1 (manuscript under preparation) and XRCC1 18 are key predictor of platinum resistance in ovarian cancers." (PMID 34373746, 2021). "FEN1 expression was also significantly higher in ovarian cancer cell lines (SKOV3, CaOV3, and OVCAR3) than in the non-cancerous cell line (HOSEpiC)." (PMID 35246224, 2022). "However, FEN1 is also upregulated in numerous tumors, including BC, non-small-cell lung cancer (NSCLC), and ovarian cancer." (PMID 34277392, 2021).
colorectal cancer (15 papers, 2013 to 2025). A primary or metastatic malignant neoplasm that affects the colon or rectum. "In summary, the current study uncovers the functional involvement of FEN1 in colorectal cancer susceptibility through the DNA replication process and highlights the effect of the causal variant rs4246215 G>T on the colorectal tumor immune microenvironment." (PMID 38111199, 2023). "Our team identified the FEN1 mutation in colorectal cancer cells and evaluated its function in cancer progression." (PMID 28371273, 2017). "SL has been observed in a RAD54B-deficient human colorectal cancer cell line following iatrogenic reduction of FEN1 expression." (PMID 26431531, 2015). "Moreover, a genetic variant rs4246215 G>T in FEN1 was associated with a decreased risk of colorectal cancer (odds ratio = 0.94, 95% confidence interval: 0.90–0.97, Pmeta = 4.70 × 10−9)." (PMID 38111199, 2023). "Recently, it was reported that L209P FEN1 mutation is associated with colorectal cancer." (PMID 31518347, 2019). "Myricetin (3,3′,4′,5,5′,7-Hexahydroxyflavone cannabiscetin), a class of flavonoids, acts as a FEN1 inhibitor and was sensitive to FEN1 overexpression in colorectal cancer." (PMID 35883563, 2022). "Several synthetic lethal partners for FEN1 have been identified, including MRE11 and CDC4-deficient colorectal cancers, and BRCA1/2-deficient cells, which both respond to small molecule inhibitors of FEN1." (PMID 32648895, 2020). "Inhibition of flap endonuclease activity was also found to recapitulate a genetic interaction between FEN1 and MRE11A, another gene frequently mutated in colorectal cancers, and to lead to increased endogenous DNA damage." (PMID 23382697, 2013). "We next attempted to recapitulate the interaction between FEN1 and MRE11A, as MRE11A has been shown to be mutated at a frequency of 4% in colorectal cancers." (PMID 23382697, 2013). "We observed consistent FEN1 overexpression in colorectal tumors at both the RNA and protein levels, suggesting that FEN1 may serve as a promising biomarker for the diagnosis of colorectal cancer." (PMID 38111199, 2023). "Interestingly, CHEK1 was co-expressed with minichromosome maintenance complex component (MCM family) and flap eendonuclease 1 (FEN1) expressed in colorectal cancer." (PMID 32178478, 2020). "Using siRNA-based silencing and high-content imaging they showed that diminished FEN1 (flap endonuclease 1) expression induced cellular selective cytotoxicity within RAD54B-deficient colorectal cancer cell but not in isogenic control cell line." (PMID 24202319, 2013). "In colorectal cancer cells, CYP1B1 modulates the cell cycle by affecting the expression of the PCNA and FEN1 genes, ultimately promoting proliferation." (PMID 40989158, 2025).
cervical cancer (9 papers, 2019 to 2025). A primary or metastatic malignant neoplasm involving the cervix. "MiR-140-5p can also inhibit the normal progress of cell cycle and inhibit the development of cervical cancer by down-regulating FEN1." (PMID 35883563, 2022). "The use of FEN1 inhibitors in combination with paclitaxel can significantly improve the efficacy of paclitaxel in cervical cancer." (PMID 35379200, 2022). "SC13, a specific inhibitor targeting FEN1 induced impaired DNA damage repair mechanisms that leads to cancer cell apoptosis, thereby enhancing the IR sensitivity of cervical cancer." (PMID 35883563, 2022). "Research published by Li JL suggested that inhibitors against FEN1 increase the sensitivity of cervical cancer cells to ionizing radiation therapy." (PMID 33827468, 2021). "Cervical cancer highly expressed FEN1, and inhibiting FEN1 expression can make cervical cancer cells sensitive to Paclitaxe l." (PMID 32586310, 2020). "FEN1 inhibitor enhances IR sensitivity of cervical cancer, and this enhancement effect was largely due to the impairment of DNA damage repair mechanism resulting from FEN1 inhibition, leading to apoptosis of cancer cells." (PMID 31670906, 2019). "Based on the Cancer Genome Atlas (TCGA) database, FEN1 expression level was about eightfold higher in cervical cancer samples compared to normal tissues, and was positively correlated with γH2AX expression, a DNA damage sensor." (PMID 31670906, 2019). "Our results showed that FEN1 inhibitor enhances IR sensitivity of cervical cancer both in vitro and in vivo, which confirmed the conclusion that inhibition of FEN1 can sensitize cancer cells to DNA damage‐related drugs." (PMID 31670906, 2019). "We also demonstrated that FEN1 inhibitor enhanced IR sensitivity of cervical cancer in both in vitro and in vivo models." (PMID 31670906, 2019). "We also demonstrated that FEN1 inhibitor enhances IR sensitivity of cervical cancer in vitro and in vivo." (PMID 31670906, 2019). "When cervical cancer line HeLa cells were exposed to IR, FEN1 and γH2AX expression levels were both upregulated in an IR dosage‐dependent fashion at 2 hours." (PMID 31670906, 2019). "Furthermore, cervical cancers also overexpressed FEN1, and FEN1 inhibition increased the sensitivity to ionizing radiation (IR) of cervical cancer." (PMID 38396787, 2024). "In this study, we determined whether FEN1 inhibitor SC13 could enhance the sensitivity of IR treatment in cervical cancer cells." (PMID 31670906, 2019). "Since FEN1 is overexpressed in HeLa cervical cancer cell and upregulated by IR induction, we speculated that the inhibition of FEN1 activity may sensitize IR treatment of HeLa cells." (PMID 31670906, 2019). "In this study, we determined if FEN1 inhibitor SC13 could sensitize cervical cancer cell to radiotherapy." (PMID 31670906, 2019). "We also showed that FEN1 inhibitor enhances IR sensitivity of cervical cancer both in vitro and in vivo, and the beneficial effect was largely due to the impairment of DNA damage repair mechanism resulting from FEN1 inhibition, leading to apoptosis of cancer cells." (PMID 31670906, 2019). "In this study, we sought to determine if FEN1 inhibitor could enhance the beneficial effect of IR for cervical cancer." (PMID 31670906, 2019). "It was shown that SC13 combination therapy sensitized cancer cells to low-concentration paclitaxel treatment, which meant that the side effects of paclitaxel could be avoided, and targeting FEN1 may be a new strategy for tumor-targeted therapy of cervical cancer." (PMID 35883563, 2022). "FEN1 inhibitor SC13 could sensitize radiotherapy of cervical cancer cell." (PMID 31670906, 2019). "Interestingly, we observed that FEN1, PCNA, RAD51 and RPA1 protein levels were upregulated in cervical cancer derived cell lines as well as in keratinocytes transduced with HPV16 oncogenes when compared to normal PHK." (PMID 30674977, 2019).
osteosarcoma (8 papers, 2013 to 2025). A usually aggressive malignant bone-forming mesenchymal neoplasm, predominantly affecting adolescents and young adults. "Therefore, human osteosarcoma (HOS) cells were transfected with Fen1 variants, tagged with hemagluttinin (HA) at their carboxyl-termini." (PMID 23675412, 2013). "In osteosarcoma cells, the miR-193b/FEN1 axis activates autophagy and induces apoptosis, which are related to the sensitivity of epirubicin to chemotherapy." (PMID 33827468, 2021). "In osteosarcoma, mir-193b /FEN1 axis increased the sensitivity of osteosarcoma cells to Epirubicin by inducing autophagy and apoptosis." (PMID 32586310, 2020). "In addition, recent studies have also shown that FEN1 knockdown induces apoptosis through the activation of autophagy, which enhances the anticancer effects of epirubicin in osteosarcoma." (PMID 37326412, 2023).